SCYGR10 (small cysteine and glycine repeat containing 10 (gene/pseudogene))
Description:
In the hair cortex, hair keratin intermediate filaments are embedded in an interfilamentous matrix, consisting of hair keratin-associated proteins (KRTAP), which are essential for the formation of a rigid and resistant hair shaft through their extensive disulfide bond cross-linking with abundant cysteine residues of hair keratins. The matrix proteins include the high-sulfur and high-glycine-tyrosine keratins.
Synonyms: KRTAP28p2; KRTAP28-10
Gene: Protein-coding gene on chromosome 2 (227,608,784 to 227,609,101, forward strand). Ensembl gene ENSG00000284622.